IL11 (interleukin 11)
Diseases named in the same sentence as IL11 in open-access papers (continued):
Sharing a sentence is not in itself a finding about the gene and the disease.
metastatic disease (2 papers, 2022 to 2024). "Biomarkers like IL-6, IL-8, IL-1β, and IL-11 offer opportunities for early detection, patient stratification, and personalized treatment approaches, enhancing the clinical management of metastatic disease." (PMID 39125732, 2024).
myeloid malignancies (2 papers, 2012 to 2023). "Another approach involves using recombinant human interleukin-11 (rhIL-11), which has received FDA approval for the treatment of CIT in non-myeloid tumors." (PMID 38041150, 2023).
nephritis (2 papers, 2023). Inflammation of renal tissue. "In addition, urinary IL11 levels are increased in patients with nephritis and IL11 is highly up-regulated in the kidneys of patients with end stage renal failure." (PMID 38054591, 2023).
neuroblastoma (2 papers, 2014 to 2024). Neuroblastoma (NB) is the most common solid, extracranial childhood tumor. "Cytokines selected from primary, secondary, and tertiary clusters with respect to EPO (IL-11, KITLG, LIF, THPO) were chosen as experimental candidates, to test their effect on Egr2 mRNA expression in serum-starved EPOR-B104 neuroblastoma cells exactly." (PMID 24672526, 2014). "Given the numerous pathways activated by IL11 signalling (the ligand of IL11RA), including JAK-STAT, Ras-MAPK, PI3K-AKT, and NF-κB, the complexity of signalling and interaction could mean tissue- and pathway-specificity for the effect of IL11RA upregulation on neuroblastoma." (PMID 38398114, 2024).
oesophageal cancer (2 papers, 2019 to 2023). "Considering the mechanism by which IL‐11 influences cancer has been thoroughly studied, we aimed to investigate the mechanism by which HOTAIR acting as a ceRNA of miR‐204 regulates the expression of HOXC8 in oesophageal cancer cells." (PMID 31389660, 2019). "Through the integration of data information, it was found that the variable shear factor QKI was closely related to the epithelial mesenchymal transformation (EMT) of oesophageal cancer, and QKI might promote the EMT process by activating the expression of IL-11, MFAP2, MMP10 and MMP1." (PMID 37428781, 2023).
renal cell carcinoma (2 papers, 2020 to 2024). "In renal cell carcinoma K8 overexpression promoted cell migration and invasion by increasing the expression of IL-11 and triggering the STAT3-signaling pathway, establishing the significance of KRT8-IL-11 axis in metastasis." (PMID 33171868, 2020).
sarcopenia (2 papers, 2023 to 2024). Progressive decline in muscle mass due to aging which results in decreased functional capacity of muscles. "Our studies of healthspan identified IL11 as an inflammaging factor that causes ERK/mTOR-mediated sarcopenia, metabolic dysfunction and frailty in old mice, while showing that therapeutic targeting of IL11 increases mouse healthspan." (PMID 38054591, 2023). "Beyond metabolism, inhibition of IL-11 improved deterministic features of ageing that are common among vertebrates (such as frailty and sarcopenia), showing generic anti-ageing benefits at the organismal level." (PMID 39020175, 2024).
tuberculosis (2 papers, 2011 to 2022). A chronic, recurrent infection caused by the bacterium Mycobacterium tuberculosis. "IL-11 is multifunctional cytokine whose physiological role in the lungs during pulmonary tuberculosis (TB) is poorly understood." (PMID 21789190, 2011). "The role of IL-11 during pulmonary tuberculosis (TB) and accompanying lung inflammation is poorly understood." (PMID 21789190, 2011).
Ureteral obstruction (2 papers, 2022 to 2023). Obstruction of the flow of urine through the ureter. "Administration of Il11 shRNA reduced pathogenic signaling and fibrosis while restoring E-cadherin levels, whereas overexpression of exogenous mouse IL-11 exacerbated unilateral ureteric obstruction–induced pathologies." (PMID 37816442, 2023). "In a mouse model of unilateral ureteric obstruction, the authors observed an up-regulation of Il11 and Il11ra1 RNA that was mostly localized to RTECs." (PMID 37816442, 2023).
vitamin D deficiency (2 papers, 2022 to 2024). A nutritional condition produced by a deficiency of VITAMIN D in the diet, insufficient production of vitamin D in the skin, inadequate absorption of vitamin D from the diet, or abnormal conversion of vitamin D to its bioactive metabolites. "The association of vitamin D deficiency and TGFβ1/IL-11/p-MEK/p-ERK-dependent fibrosis was also observed in a genetic mouse model of vitamin D deficiency mimicking some effects of FGF-23 overproduction." (PMID 38732588, 2024).
abortion (1 paper, 2004). the ending of pregnancy by removing a fetus or embryo before it can survive outside the uterus. "Plasma levels of IL-11 are decreased in women with first trimester spontaneous abortion, and there is decreased expression of IL-11 protein in chorionic villi and decidua from anembryonic compared to normal pregnancy." (PMID 15537430, 2004).
acute leukemia (1 paper, 2023). A clonal (malignant) hematopoietic disorder with an acute onset, affecting the bone marrow and the peripheral blood. "This study mainly explored the efficacy of recombinant human IL-11 in preventing and treating OM in patients with acute leukemia, with good therapeutic effects." (PMID 37438702, 2023). "The main purpose of this study was to investigate the preventive and therapeutic effects of IL-11 oral gargle on OM in patients with acute leukemia following chemotherapy." (PMID 37438702, 2023). "IL-11 gargle reduced the severity of OM after chemotherapy for acute leukemia." (PMID 37438702, 2023). "In this study, patients with acute leukemia who were treated with chemotherapy were selected as research subjects to observe the occurrence time, severity, pain, degree, duration, mucosal healing time, and effects of OM after topical treatment with IL-11 gargle on eating." (PMID 37438702, 2023).
Airway obstruction (1 paper, 2021). Obstruction of conducting airways of the lung. "IL-11 was suggested that could cause lung inflammation and airway obstruction." (PMID 34809630, 2021).
Allergy (1 paper, 2022). An allergy is an immune response or reaction to substances that are usually not harmful. "Thus, IL11 upregulation in inflammatory human diseases is unlikely to be a compensatory response, as suggested previously, and can instead be expected to contribute to allergy and inflammation as part of a broader alarmin response." (PMID 36012165, 2022).
Aortic dissection (1 paper, 2023). Aortic dissection refers to a tear in the intimal layer of the aorta causing a separation between the intima and the medial layers of the aorta. "In a previous study, the level of IL-11 in plasma and thoracic aorta (especially in the torn segment of aortic dissection) of patients with acute thoracic aortic dissection increased." (PMID 37304948, 2023).
aplastic anemia (1 paper, 2017). Anemia resulting from bone marrow failure (aplastic or hypoplastic bone marrow). "In conclusion, IL-11 stimulates HSC proliferation and increases TPO expression in vitro, which may explain the stimulating role of IL-11 treatment on HSC transplantation in a mouse model of aplastic anemia." (PMID 29217821, 2017).
Arterial stenosis (1 paper, 2021). Narrowing or constriction of the inner surface (lumen) of an artery. "This suggests IL-11 inhibition as a potential novel therapeutic approach to reduce arterial stenosis following revascularization in CAD and PAD patients." (PMID 34667238, 2021).
Autoimmunity (1 paper, 2023). The occurrence of an immune reaction against the organism's own cells or tissues. "IL-11 may induce Th17 cells generation and expansion in vitro and Th17 cells responses in vivo and contribute to autoimmunity." (PMID 37894114, 2023).
autosomal dominant HIES (1 paper, 2023). "IL-11 plays a role in bone development accounting for the cranial abnormalities seen in STAT3-associated autosomal dominant HIES." (PMID 38133879, 2023).
bacterial pneumonia (1 paper, 2019). Acute infection of the lung parenchyma caused by bacteria (e.g., Streptococcus pneumoniae, Haemophilus influenzae, Chlamydia pneumoniae, Mycoplasma pneumoniae, and Legionella pneumophila). "Given the previously established role of IL-11 in other inflammatory contexts as well as the known importance of other select IL-6 family members, we investigated the functional contributions of IL-11 in the setting of bacterial pneumonia." (PMID 31415618, 2019).
Barrett esophagus (1 paper, 2020). Esophageal lesion lined with columnar metaplastic epithelium which is flat or villiform. "The molecular mechanism of IL‐11 in esophageal adenocarcinoma is the focus of our future research." (PMID 32869505, 2020).
bladder cancer (1 paper, 2021). "Recently, Chen and colleagues reported that lncRNA DANCR directly interacted with LRPPRC and guided LRPPRC protein to bind and stabilize the mRNAs of CCND1, PLAU, and IL-11, resulting in enhanced proliferation, migration, and invasion of bladder cancer cells." (PMID 34671012, 2021).
bone marrow failure (1 paper, 2017). "As benzene toxicity appears to primarily affect hematopoietic cell survival, the finding that IL-11 promotes HSC engraftment in benzene-induced bone marrow failure was consistent with the in vitro effects of IL-11 on HSC proliferation." (PMID 29217821, 2017).
brain cancer (1 paper, 2024). A primary or metastatic malignant neoplasm affecting the brain. "We also found that the expression of the onco-immune factors (ENO1, MUC1, COL5A1, IL11) that we identified was significantly correlated with FABP7 expression in patient brain cancers, particularly LGG, suggesting the pathological relevance of the results of our transcriptomic analyses." (PMID 39596296, 2024). "Notably, genes linked to brain cancer progression and tumor immunity (ENO1, MUC1, COL5A1, and IL11) were significantly downregulated (>2-fold) in KO brain tissue but were upregulated in FABP7 OV astrocytes." (PMID 39596296, 2024).
bronchial carcinoma (1 paper, 2024). "However, it should be noted that IL-11 levels have also been non-detectable in plasma or serum in patients with lung pathologies, including bronchial carcinoma." (PMID 39329890, 2024).
cerebrovascular disorder (1 paper, 2023). A disorder resulting from inadequate blood flow in the vessels that supply the brain. "More studies are needed to determine the precise role of IL-11 in cerebrovascular disorders and its mechanisms." (PMID 37304948, 2023).
Chlamydia infection (1 paper, 2021). "However, basal IL11 transcript levels were similar between primary epithelial cells and HeLa cells, and showed similar induction by Chlamydia infection in the two cellular backgrounds." (PMID 33712643, 2021).
chlamydial infection (1 paper, 2014). "Studies investigating the cytokine and chemokine response to chlamydial infection have shown up-regulation of IL-1α, IL-6, IL-11, TGF-β1, GM-CSF, GRO-α and IL-8 in C. trachomatis-infected HeLa cells." (PMID 25019934, 2014).
chondrosarcoma (1 paper, 2024). A malignant cartilaginous matrix-producing mesenchymal neoplasm arising from the bone and soft tissue. "In addition, IL-11 stimulation led to enhanced cell motility in chondrosarcoma tumour cells, and knockdown of either IL-11Rα or GP130 in these cells significantly reduced migration." (PMID 38248304, 2024).
chordoma (1 paper, 2023). Chordomas are rare malignant tumors arising from embryonic remnants of the notochord in axial skeleton. "Genes marked on the volcano plot were either implicated earlier in chordoma biology (e.g. keratins—KRT8, KRT18, KRT19, TBXT, LMX1A, and EGFR) or identified by outstanding p-value (e.g. IL11, CD24), high absolute fold-change (e.g. GABRA1) or DMR result (e.g. MNX1)." (PMID 37434245, 2023).
chronic pancreatitis (1 paper, 2022). A chronic inflammatory process causing damage and fibrosis of the pancreatic parenchyma. "We suggest that the elevated levels of IL11 in acinar cells in chronic pancreatitis could be linked with additional effects of IL11 in the pancreas, outside of the stroma." (PMID 35408908, 2022). "As such, both IL11 and its receptor are upregulated in the pancreases of patients with chronic pancreatitis." (PMID 35408908, 2022). "In mice, IL11 was increased in the pancreas after pancreatic duct ligation, and in humans, IL11 and IL11RA levels were elevated in chronic pancreatitis." (PMID 35408908, 2022). "We investigated the expression of IL11 and IL11RA in human pancreatitis by performing immunostaining for IL11 and IL11RA in pancreatic tissue sections from patients with chronic pancreatitis and from a control individual." (PMID 35408908, 2022). "Our analysis of human pancreatic tissues, although limited, revealed that IL11 and IL11RA are increased in chronic pancreatitis." (PMID 35408908, 2022). "IL11 was not detectable in control pancreases, but was readily detected in pancreatic sections from patients with chronic pancreatitis." (PMID 35408908, 2022).
colon adenocarcinoma (1 paper, 2025). "One of the mechanisms proposed for IL‐11 mediating immune evasion is a suppression of the anti‐tumoural functions of CD4+ Th1 cells, thereby favouring tumour progression in a mouse model for colon adenocarcinoma." (PMID 40673604, 2025).
colon adenoma (1 paper, 2021). An adenoma that arises from the colon. "However, in our present study, anti-TGFβ antibody treatment did not downregulate Il11 expression in colonic adenomas of Apcmin/+ mice or in AOM/DSS-induced CAC." (PMID 33863879, 2021). "Overall, although TGFβ per se was able to induce IL-11 production, TGFβ may not be involved in the induction of IL-11+ fibroblasts in the present tumor models, including AOM/DSS-induced CAC and colon adenoma in ApcMin/+ mice." (PMID 33863879, 2021).
colorectal adenocarcinoma (1 paper, 2010). The most common type of colorectal carcinoma. "Similarly, IL11 and IL11Rα protein are highly expressed in human colorectal adenocarcinoma and IL11Rα levels correlate with clinicopathological factors." (PMID 20553623, 2010).
coronary atherosclerosis (1 paper, 2020). Atherosclerosis of the coronary vasculature. "Similarly, serum IL11 was found to be raised in patients with coronary atherosclerosis and unstable angina, which might reflect its secretion from dysfunctional coronary artery VSMCs19,50." (PMID 33082445, 2020).
coronary stenosis (1 paper, 2019). Narrowing of the coronary artery lumen diameter. "In CAD patients, IL-11 is even associated with the Gensini score, which can be used to estimate the severity of coronary stenosis." (PMID 30728748, 2019).
differentiated thyroid carcinoma (1 paper, 2016). Differentiated thyroid carcinoma (DTC), also known as papillary or follicular thyroid carcinoma, is a slow-growing malignancy usually presenting in adults as an asymptomatic thyroid mass. "The 71.1% of ATCs display IL-11 expression, which was significantly higher than that for the papillary thyroid carcinoma, and may help explain the high rates of ATC metastasis." (PMID 27487122, 2016).
endophthalmitis (1 paper, 2024). An infectious process affecting the internal structures of the eye. "In an intradermal infection mice model, IL-1β, IL-6, TNF-α, and IFN-γ were produced by the lymph nodes only after MSSA infection; while in a murine model of endophthalmitis, IL-10, IL-15, IL-11, and some chemokines and receptors were significantly strongly upregulated by MRSA." (PMID 38571946, 2024).
enteritis (1 paper, 2021). Inflammation of the small intestine. "Co‐culture with intraperitoneal macrophages from mice with DSS‐induced enteritis significantly increased the levels of inflammatory factors (IL‐6, IL‐11, IL‐22, TNF‐α) in colonic epithelial cells compared to macrophages from healthy mice, whereas GW4868 eliminated this difference." (PMID 33569850, 2021).
enterocolitis (1 paper, 2021). An inflammatory process affecting the small intestine and colon. "Furthermore, IL-11 gene polymorphisms may play a role in HSCR-associated enterocolitis." (PMID 33468134, 2021).
fungal infection (1 paper, 2022). "The antifungal cytokines—Type1 (IL-7 and IL-15), Th17 (IL-7), and proinflammatory (IL-11)—were all significantly enhanced in CBM patients, presumably as a compensatory response to the long-term fungal infection." (PMID 35252030, 2022).
giant cell arteritis (1 paper, 2023). "In an epigenomic analysis of CD14+ mononuclear cells from giant cell arteritis patients, a previous study found increased responsiveness of DNA differential methylation regions in the IL-11 pathway in patients in the active stage compared to the control group and patients in the remission stage." (PMID 37304948, 2023).
graft versus host disease (1 paper, 2015). An immune system disorder that occurs after allogeneic hematopoietic stem cell transplant and is a reaction of donor immune cells against host tissues. "Clinically, it has been shown that IL-11 can decrease the occurrence of the development of graft versus host disease (GVHD), which is induced by allogeneic hematopoietic stem cell transplantation (allo-HSCT)." (PMID 26528857, 2015).
Granuloma (1 paper, 2024). A compact, organized collection of mature mononuclear phagocytes, which may be but is not necessarily accompanied by accessory features such as necrosis. "Compared to “healthy” lung parenchyma, the concentration of proinflammatory cytokines IL-6, IL-11, IL-17, and IFNγ, which are responsible for granuloma organization and infection focus delineation, was increased in the tuberculoma wall." (PMID 39519346, 2024).
Helicobacter infection (1 paper, 2013). "Therefore in contrast to gp130-mediated antral tumors driven by the IL-6 family member IL-11, we show here that Helicobacter infection drives IL-6 expression and SPEM." (PMID 23520544, 2013).
Hermansky-Pudlak syndrome (1 paper, 2023). Hermansky-Pudlak syndrome (HSP) is a multi-system disorder characterized by oculocutaneous albinism, bleeding diathesis and, in some cases, neutropenia, pulmonary fibrosis, or granulomatous colitis. "Similarly, IL11 alone induced fibrotic changes in healthy alveolar organoids whereas knock-out of IL11 expression in diseased organoids reversed organoid fibrosis in a model of the Hermansky-Pudlak syndrome-associated interstitial pneumonia, a disease with high similarity to IPF." (PMID 37266432, 2023).
Hydrocephalus (1 paper, 2021). Hydrocephalus is an active distension of the ventricular system of the brain resulting from inadequate passage of CSF from its point of production within the cerebral ventricles to its point of absorption into the systemic circulation. "Additionally in ICH, CSF IL-11 levels were higher in patients with hydrocephalus occurring after ICH onset and were also associated with high mortality." (PMID 34685473, 2021).
Hypercholesterolemia (1 paper, 2021). An increased concentration of cholesterol in the blood. "Similarly, in the WDF model, restoration of hepatocyte-specific IL11 cis-signaling (mIL11RA) in KO mice caused hyperglycemia, hypertriglyceridemia, and hypercholesterolemia but expression of sIl11ra1 did not." (PMID 33397952, 2021).
Hypoalbuminemia (1 paper, 2011). The concentration of albumin in the blood circulation is below the lower limit of normal. "Hypoalbuminemia and lower blood pressure occurred soon after the initiation of IL-11 and serum Cr was also increased because of hypovolemia." (PMID 21619578, 2011).
ischemia reperfusion injury (1 paper, 2015). Adverse functional, metabolic, or structural changes in ischemic tissues resulting from the restoration of blood flow to the tissue (reperfusion), including swelling; hemorrhage; necrosis; and damage from free radicals. "IL-11 has displayed protective roles during ischemia-reperfusion injury (IRI) in the heart, kidney and intestine, but a similar role has not been elucidated in liver IRI." (PMID 25946003, 2015).